ST8SIA3 (ST8 alpha-N-acetyl-neuraminide alpha-2,8-sialyltransferase 3)
Description:
Catalyzes the transfer of sialic acid from a CMP-linked sialic acid donor onto a terminal alpha-2,3-, alpha-2,6-, or alpha-2,8-linked sialic acid of an acceptor, such as N-linked oligosaccharides of glycoproteins and glycolipids through alpha-2,8-linkages. Forms oligosialic and polysialic acid on various sialylated N-acetyllactosamine oligosaccharides of glycoproteins, including FETUB N-glycans, a2-HS-glycoprotein (AHSG) and alpha 2,3-sialylated glycosphingolipids, such as alpha 2,3-sialylparagloboside and ganglioside GM3 and to a lesser extent NCAM1 N-glycans. However, it is much more specific to N-linked oligosaccharides of glycoproteins than glycosphingolipids (By similarity). 2,3-sialylparagloboside serves as the best acceptor substrate among the glycolipids (By similarity). alpha-Neu5Ac-(2->8)-alpha-Neu5Ac-(2->3)-beta-D-Gal-(1->4)-6S-D-GlcNAc and monosialyl and disialyl N-acetyllactosamines are the best acceptor substrates among glycoproteins. May play a critical role in the striatum by mediating the formation of disialylated and trisialylated terminal glycotopes on N- and O-glycans of specific striatal proteins, regulating their distribution in lipid rafts, affecting their interaction with other binding partners, and subsequently modulating striatal functions (By similarity).
Synonyms: ST8SiaIII; SIAT8C
Tractability: Small molecule: a structure with a bound ligand is known. Antibody: UniProt predicts a signal peptide or a membrane-spanning region. PROTAC: its protein half-life has been measured.
Gene: Protein-coding gene on chromosome 18 (57,352,557 to 57,371,731, forward strand). Ensembl gene ENSG00000177511.
Subcellular location: Golgi apparatus membrane
Subcellular location (Human Protein Atlas): Golgi apparatus
Pathways (Reactome):
Metabolism of proteins: N-Glycan antennae elongation; Sialic acid metabolism
Gene Ontology:
Molecular function: alpha-N-acetylneuraminate alpha-2,8-sialyltransferase activity; identical protein binding; sialic acid binding; sialyltransferase activity
Biological process: ganglioside biosynthetic process; glycoprotein biosynthetic process; glycoprotein metabolic process; N-glycan processing; oligosaccharide metabolic process; sialylation; glycosphingolipid biosynthetic process
Cellular component: Golgi apparatus; Golgi membrane
Genetic constraint (gnomAD): Loss-of-function variants: 16 observed, 33.05 expected, observed/expected ratio (o/e) 0.48, 90% interval 0.33 to 0.74. The upper end of that interval is the gene's LOEUF score, 0.74, which puts it in group 3 of 6, group 1 being the genes least tolerant of losing a copy. Missense variants: 352 observed, 487.86 expected, observed/expected ratio (o/e) 0.72, 90% interval 0.66 to 0.79. Synonymous variants: 172 observed, 184.3 expected, observed/expected ratio (o/e) 0.93, 90% interval 0.82 to 1.06.
Homologues: Orthologues: chimpanzee ST8SIA3 (99% identical), macaque ST8SIA3 (99% identical), dog ST8SIA3 (98% identical), mouse St8sia3 (98% identical), rat St8sia3 (98% identical), pig ST8SIA3 (96% identical), tropical clawed frog st8sia3 (91% identical), rabbit ST8SIA3 (87% identical), guinea pig ST8SIA3 (83% identical), zebrafish st8sia3 (79% identical). Paralogues in human: ST8SIA2 (34% identical), ST8SIA4 (33% identical), ST8SIA6 (29% identical), ST8SIA1 (26% identical), ST8SIA5 (26% identical).
Diseases named in the same sentence as ST8SIA3 in open-access papers:
ST8SIA3 is named in the same sentence as 13 diseases in open-access papers, as found by Europe PMC text mining. Sharing a sentence is not in itself a finding about the gene and the disease. The quoted sentences say what the papers report.
glioblastoma (4 papers, 2022 to 2025). The most malignant astrocytic tumor (WHO grade IV). "In glioblastoma, ST8SIA3 overexpression is linked to the synthesis of the A2B5 sialoganglioside, promoting cancer stem cell properties such as enhanced proliferation and tumor growth." (PMID 39860532, 2025). "ST8SIA3 is expressed at very low levels compared to intracranial tumors according to the TNMplot data, although ST8SIA3 has been shown to promote survival, proliferation, and migration of glioblastoma cells based on ST8SIA3 knockdown experiments in vitro." (PMID 38067186, 2023). "Consistent with ST8SIA3 as a risk factor in the present study, it mediates the sialylation of GM3 and GD3 and promotes survival, proliferation, clonogenicity, and migration of glioblastoma cells." (PMID 36605200, 2022). "ST8SIA3 was proved to participate in the synthesis of A2B5 epitope and was critical for A2B5 immunoreactivity in glioblastoma, indicating the potential of neuraminidase treatment." (PMID 36611197, 2023).
glioma (2 papers, 2022 to 2023). A benign or malignant brain and spinal cord tumor that arises from glial cells (astrocytes, oligodendrocytes, ependymal cells). "However, EXTL1, ST8SIA3, and GALNT9 demonstrated a negative relation with oncogenic pathways, suggesting a potentially protective role for glioma progression." (PMID 37663248, 2023).
Huntington disease (2 papers, 2019 to 2023). Huntington disease (HD) is a rare neurodegenerative disorder of the central nervous system characterized by unwanted choreatic movements, behavioral and psychiatric disturbances and dementia. "Because ST8SIA3 is enriched in the striatum, it has been implicated in Huntington’s disease (HD), a devastating neurodegenerative disease." (PMID 31455764, 2019). "ST8SIA3 (alpha-N-acetyl-neuraminide alpha-2,8-sialyltransferase 3) is involved in neurite growth, cell migration, and synaptic plasticity and plays an important role in the development of Huntington’s disease, schizophrenia, and Parkinson’s disease." (PMID 36845551, 2023).
Parkinson disease (2 papers, 2019 to 2023). A progressive degenerative disorder of the central nervous system characterized by loss of dopamine producing neurons in the substantia nigra and the presence of Lewy bodies in the substantia nigra and locus coeruleus. "Since the A2AR-D2R heteromer is an important drug target for several basal ganglia diseases (such as schizophrenia and Parkinson’s disease), the present study not only reveals a crucial role for ST8SIA3 in striatal functions but also provides a new drug target for basal ganglia-related diseases." (PMID 31455764, 2019).
breast carcinoma (1 paper, 2016). "Of these, three genes have higher expression in the tumor tissues including ST6GALNAC5 (2.31-folds), ST8SIA3 (1.78-folds) and ST8SIA4 (2.47-folds), suggesting that breast cancer expressed high levels of α2,6- and α2,8-linked sialylation." (PMID 28032858, 2016). "Among these, the expression of ST6GALNAC5, ST8SIA3 and ST8SIA4 was significantly upregulated in breast cancer tissues compared with adjacent tissues, and ST8SIA2 and ST8SIA6 were upregulated in the adjacent tissues." (PMID 28032858, 2016).
cancer (3 papers, 2023 to 2025). A tumor composed of atypical neoplastic, often pleomorphic cells that invade other tissues. "Unlike ST6GAL1, there are relatively few studies focusing on the relationship between ST8SIA3 and cancer." (PMID 36611197, 2023). "In addition, ST8SIA3 and GALNT9 might have an inhibitive role in cancer promotion by negatively modulating the activity of DNA damage and the EMT, PI3K/AKT, and mTOR pathways." (PMID 37663248, 2023).
tumor (3 papers, 2016 to 2025). "ST8SIA3 overexpression increased cell proliferation, migration, and clonogenicity in vitro and tumor growth when cells were intracranially grafted." (PMID 31466399, 2019). "Interestingly, ST8SIA3 overexpression shortened the overall survival and decreased 1.3-fold the median survival from 42.5 days (range 36–45) for U87-MG to 32 days (range 23–45) for U87-ST8SIA3-tumor-bearing mice (p < 0.05)." (PMID 31466399, 2019).
ST8SIA3 also shares sentences with these, for which no sentence is quoted: neurodegenerative disease (2 papers); schizophrenia (2); Cirrhosis (1); colon cancer (1); movement disorder (1); tauopathy (1).